CSPG4 (chondroitin sulfate proteoglycan 4)
Diseases named in the same sentence as CSPG4 in open-access papers (continued):
Sharing a sentence is not in itself a finding about the gene and the disease.
cardiomyopathy (1 paper, 2025). A disease of the heart muscle or myocardium proper. "By targeting CSPG4, we aim to provide preclinical evidence supporting CAR-T-based interventions for DMD-associated cardiomyopathy, offering new insights into potential therapeutic approaches for DMD-related heart failure." (PMID 40724839, 2025). "This study shows that CSPG4-targeted CAR-T cell therapy attenuates cardiac fibrosis and improves cardiac function in DMD-associated cardiomyopathy." (PMID 40724839, 2025). "Given the urgent unmet need for disease-modifying treatments in DMD cardiomyopathy, CSPG4-targeted CAR-T therapy represents a promising step toward precision medicine approaches for this devastating disorder." (PMID 40724839, 2025). "In conclusion, this study establishes a proof-of-concept for CSPG4.CAR-T therapy as a novel and targeted approach for treating DMD-associated cardiomyopathy." (PMID 40724839, 2025). "The favorable tolerability and immunomodulatory effects observed in mdx mice suggest that CSPG4.CAR-T therapy may be a viable and scalable strategy for DMD patients and potentially other dystrophy-related cardiomyopathies." (PMID 40724839, 2025).
cerebral tumours (1 paper, 2013). "This specific expression pattern suggests that NG2/CSPG4 may be an effective therapeutic target for the treatment of cerebral tumours." (PMID 24386429, 2013).
cervical cancer (1 paper, 2020). A primary or metastatic malignant neoplasm involving the cervix. "By using human cervical cancer cell line HeLa CSPG4 knockout (CSPG4−/−) cells as well as TcdB mutants which do not bind to either CSPG4 or frizzled-1,2,7, or both, we evaluated the impact of the individual receptors for cytopathic and cytotoxic effects of TcdB." (PMID 33255261, 2020).
chondrosarcoma (1 paper, 2022). A malignant cartilaginous matrix-producing mesenchymal neoplasm arising from the bone and soft tissue. "The current study outlines CSPG4 expression in a large series of chondrosarcoma patients showing that medium to high CSPG4 expression is associated with shorter time to metastasis and reduced overall survival in conventional and in dedifferentiated chondrosarcoma." (PMID 36110930, 2022). "Using immunohistochemistry (IHC), we stained a tissue microarray containing primary conventional and dedifferentiated chondrosarcoma from 76 patients with CSPG4 specific monoclonal antibodies (mAbs)." (PMID 36110930, 2022). "The expression of CSPG4 in the dedifferentiated chondrosarcoma is less than the CSPG4 expression of conventional chondrosarcoma (P<0.001)." (PMID 36110930, 2022). "Of the 3 conventional chondrosarcoma metastases, 2 showed a high expression of CSPG4 and 1 metastasis showed a medium expression." (PMID 36110930, 2022). "There appears to be a biphasic pattern where CSPG4 expression increases with histological grade from enchondroma up to grade 2 and begins to decrease in grade 3 and in dedifferentiated chondrosarcoma." (PMID 36110930, 2022). "Our results showed medium to high expression of CSPG4 in 29 of 41 (71%) conventional chondrosarcoma tumors and in 3 of 20 (15%) dedifferentiated chondrosarcoma tumors." (PMID 36110930, 2022). "Nonetheless, our findings are consistent with published reports on CSPG4 as a prognostic marker in cancer and provide a rationale for future studies to investigate the effectiveness of CSPG4 directed therapy in chondrosarcoma in vivo." (PMID 36110930, 2022). "Taken together, these findings support the role of CSPG4 as a promoter of disease and therefore as a clinically relevant target in patients with chondrosarcoma." (PMID 36110930, 2022). "The goal of this study was to assess the prevalence of CSPG4 in human chondrosarcoma and to assess the efficacy of CSPG4 specific CAR T cells in lysing chondrosarcoma cells in vitro." (PMID 36110930, 2022). "In the dedifferentiated chondrosarcoma 3 out of 20 tumors, show positive (medium or high) CSPG4 expression (15%)." (PMID 36110930, 2022). "Similar dose-dependent increases in tumor lysis were observed in SW1353 chondrosarcoma cells, with 70% tumor lysis in CSPG4 CAR T cell treated cells at an E:T ratio of 1:1 versus <5% tumor lysis in the CD19 CAR T cell treated group." (PMID 36110930, 2022). "CSPG4 CAR T treated cell lines showed a lysis of respectively >80% and 70% demonstrating CSPG4-targeted CAR T cells effective in killing CSPG4-positive chondrosarcoma tumors." (PMID 36110930, 2022). "Twenty-nine of the 41 (71%) conventional chondrosarcoma available for analysis show a positive (medium or high) CSPG4 expression." (PMID 36110930, 2022). "All 4 dedifferentiated chondrosarcoma metastasis showed a low CSPG4 expression." (PMID 36110930, 2022). "In addition we investigated the effectiveness of CSPG4-specific CAR T cell therapy in eliminating chondrosarcoma cells in 2 chondrosarcoma cell lines." (PMID 36110930, 2022). "In addition, we incubated 2 chondrosarcoma cell lines with CSPG4-targeting CAR T cells and subsequently evaluated cell survival." (PMID 36110930, 2022). "CSPG4 directed therapies might be particularly attractive in cases of high-grade conventional chondrosarcoma, local recurrence, and metastasis." (PMID 36110930, 2022). "The results of this study demonstrate that CSPG4 directed therapies may be applicable to chondrosarcomas with over 70% of patients in our cohort demonstrating moderate to high expression in conventional chondrosarcoma." (PMID 36110930, 2022). "Chondroitin sulfate proteoglycan 4 (CSPG4) is a cell surface proteoglycan that is highly expressed across various human cancers, including chondrosarcoma, and has restricted distribution in healthy tissues, making it an attractive target for the antibody-based therapy." (PMID 36110930, 2022).
chondrosarcoma (continued). "In the dedifferentiated chondrosarcoma cohort, we observed a shorter time to metastasis in subjects who had medium and high CSPG4 expression when compared to subjects with low or no CSPG4 expression in chondrosarcoma tissues, (p=0.048)." (PMID 36110930, 2022). "Overall survival was shorter in subject who exhibited medium and high CSPG4 expression compared to subjects with low or no CSPG4 expression in chondrosarcoma tissues (p=0.024)." (PMID 36110930, 2022). "Furthermore, we can increase CSPG4 expression in CS1 and SW1353 chondrosarcoma cells with one subclinical dose of irradiation (10 Gy) suggesting that CSPG4 CAR T efficacy may further be augmented when combined with irradiation." (PMID 36110930, 2022).
clear cell renal carcinoma (1 paper, 2024). A malignant epithelial neoplasm of the kidney characterized by the presence of lipid-containing clear cells within a vascular network. "We also found that CAFs interact uniquely with VM cells and tumor cells via HGF/MET and CSPG4 signaling pathways in clear cell renal carcinoma, and its effect on VM cells is significantly higher." (PMID 38694917, 2024).
colitis (1 paper, 2022). Inflammation of the colon. "Quantification of the immunohistochemically stained tissue areas supported the HPLC data and confirmed an increase of HA and a decrease of CSPG4 in colon tissue of mice with DSS-induced colitis." (PMID 35903065, 2022).
congenital muscular dystrophy (1 paper, 2014). A muscular dystrophy that is characterized by diminished muscle tone (hypotonia), progressive muscle weakness and degeneration (atrophy), abnormally fixed joints, spinal rigidity, and delays in reaching motor milestones such as sitting or standing unassisted. "The expression of CSPG4 in muscle cells together with the fact that it is upregulated in Duchenne muscular dystrophy, and downregulated in merosin-deficient congenital muscular dystrophy (MDC1A) muscles, respectively, suggest that Perd function in myofibrillogenesis might be conserved." (PMID 24794494, 2014).
cyst (1 paper, 2014). A sac-like closed membranous structure that may be empty or contain fluid or amorphous material. "As the SCA cyst epithelium overexpresses a number of hypoxic markers, we sought to determine whether CSPG4 might represent a novel hypoxia-regulated gene." (PMID 24932730, 2014). "It is most likely that (membranous) CSPG4 marks definite epithelial lineage, different from that of an adult pancreatic cell and prone to cyst formation upon ‘pseudo-hypoxic’ CSPG4 overexpression in association with transforming pVHL, HIF1AN and LKB1 mutations." (PMID 24932730, 2014).
delirium (1 paper, 2018). A disorder characterized by confusion; inattentiveness; disorientation; illusions; hallucinations; agitation; and in some instances autonomic nervous system overactivity. "There were markers in both serum and CSF that differed between the affected and non-affected patients (SCI; IL6, GFAP, CSPG4, delirium; TR4, EZH2, hallucinations; NF1)." (PMID 30367354, 2018).
depression (1 paper, 2019). "Genetic variation in CSPG4 might confer a pleiotropic risk for mental illness since two of the CSPG4A131T mutation carriers identified in the general population Rotterdam Study cohort had a clinically significant history of depression." (PMID 29302076, 2019).
desmoplastic melanoma (1 paper, 2013). A melanoma of the skin characterized by a proliferation of atypical spindled melanocytes in the dermis, in a background of abundant collagen. "CSPG4 is, however, a sensitive marker for desmoplastic melanoma; 95% of desmoplastic primary lesions stained for CSPG4, and 86% of nodal metastases were CSPG4 positive." (PMID 24069584, 2013).
developmental delay (1 paper, 2011). "Overexpression of the LINGO-1 and CSPG4 genes has been implicated in developmental delay seen in other patients with trisomy of 15q24-qter, but our patient is currently too young to ascertain developmental progress." (PMID 23074681, 2011).
endometrial cancer (1 paper, 2022). Primary or metastatic malignant neoplasm involving the endometrium (mucous membrane that lines the endometrial cavity). "So, again, this is an example of indirect role of IL-11 in endometrial cancer progression via CSPG4." (PMID 34951691, 2022). "Silencing CSPG4 gene expression decreased endometrial cancer cell proliferation; this is an example of indirect role of IL-11 in endometrial cancer progression via CSPG4." (PMID 34951691, 2022). "Silencing CSPG4 gene expression decreased endometrial cancer cell migration." (PMID 34951691, 2022).
endometriosis (1 paper, 2025). The growth of functional endometrial tissue in anatomic sites outside the uterine body. "CSPG4 and CS-56 showed significantly higher expression in the epithelium of endometriosis samples, while HEP was more highly expressed in the epithelium of normal samples." (PMID 40076699, 2025). "The study examined the expression of CSPG4 (chondroitin sulfate proteoglycan 4), CS-56 (a chondroitin sulfate), HEP (heparan sulfate), keratan sulfate, and hyaluronic acid in endometriosis-affected tissues compared to normal endometrium." (PMID 40076699, 2025).
gastric cancer (1 paper, 2022). A primary or metastatic malignant neoplasm involving the stomach. "Although STF1 and STF3 clusters exhibited upregulation of FAP, ACTA2, and TAGLN, the STF2 cluster exhibited upregulation of only CSPG4, further indicative of distinct CAF sublineages in gastric cancer." (PMID 34642171, 2022).
intervertebral disc degeneration (1 paper, 2021). "However, the underlying molecular mechanisms of CHST3 and CSPG4 in CESCs of intervertebral disc degeneration remain unresolved and needs further investigation." (PMID 33993645, 2021). "Co‐IP analysis demonstrated that there was an interaction between CHST3 and CSPG4 in the tissues of intervertebral disc degeneration." (PMID 33993645, 2021). "In this study, we performed bioinformatic analysis of GSE15227 database using grade II, III and IV intervertebral disc degeneration, and we choose CHST3 and CSPG4 as the main targets in the following investigation." (PMID 33993645, 2021). "CHST3 overexpression promoted CESCs to regulate bone marrow cells through interaction with CSPG4 to repair the grade II, III and IV intervertebral disc degeneration." (PMID 33993645, 2021). "This phenomenon demonstrated that the differential expression of CHST3 and CSPG4 interacted with each other and their low expression contributed to the pathogenesis of grade II, III and IV intervertebral disc degeneration." (PMID 33993645, 2021). "We performed GO and KEGG analysis of GSE15227 database to select the differential genes CHST3 and CSPG4 in grade II, III and IV intervertebral disc degeneration, IHC and WB to detect the protein profile of CHST3 and CSPG4, Co‐IP for the interaction between CHST3 and CSPG4." (PMID 33993645, 2021). "Bioinformatic analysis of GSE15227 database shows the differential gene expression of CHST3 and CSPG4 in grade II, III and IV intervertebral disc degeneration, and bioinformatics also predict the relationship between the differentially expressed CHST3 and the protein CSPG4." (PMID 33993645, 2021).
invasive breast carcinoma (1 paper, 2011). A carcinoma that infiltrates the breast parenchyma. "The expression of CSPG4 and CHST11 in 15 primary invasive breast cancer clinical specimens was assessed by qRT-PCR." (PMID 21658254, 2011).
ischemic stroke (1 paper, 2022). A stroke disorder caused by obstruction of blood flow to the brain, due to thrombotic (local blood clot formation) or embolic (due to a blood clot or other material traveling from another site) event. "Here, our findings indicated that the activation of the KDELR protein appeared to be involved in vesicular trafficking of coat protein II-mediated CSPG4 in ischemic stroke." (PMID 35927993, 2022). "Taken together, our data showed that BLR could protect against ischemic brain injury and may serve as a new promising therapeutic candidate drug for ischemic stroke, and that KDELR might act as both a sensor and effector to activate CSPG4 to increase cerebral blood flow." (PMID 35927993, 2022).
kidney (1 paper, 2023). "After UUO-induced kidney injury in 12-day-old mice, pericytes retain both CSPG4 and α-SMA expression and transdifferentiate into myofibroblasts." (PMID 36445780, 2023).
lactic acidosis (1 paper, 2022). Metabolic acidosis characterized by the accumulation of lactate in the body. "We found that both hypoxia and lactic acidosis were enhanced in "CSPG4-high" tumors." (PMID 36221119, 2022).
liver disease (1 paper, 2023). "Inhibition of Cspg4 suppresses BMSC differentiation and attenuates liver fibrosis in vitro and in vivo, which indicates NG2 as a target for the treatment of liver disease." (PMID 36674693, 2023).
liver fibrosis (1 paper, 2023). "Finally, we verified the effects of NG2 on the underlying liver fibrosis process in vivo, through the injection of chemically modified and stable Cspg4 siRNA into MCDHF mice, since fatty liver injury has become a common cause of chronic liver disease globally." (PMID 36674693, 2023). "To investigate the role of NG2 in liver fibrosis, we first examined the expression of CSPG4 in patient fibrotic livers of different etiologies and observed a significant increase in CSPG4 expression." (PMID 36674693, 2023). "Importantly, inhibition of NG2 by its specific siRNA alleviates liver fibrosis in MCDHF mice, as demonstrated by the decreased expression of fibrotic parameters, collagen deposition, serum transaminase levels, liver steatosis and inflammation after the administration of Cspg4 siRNA in MCDHF mice." (PMID 36674693, 2023).
metastatic cancer (1 paper, 2014). A carcinoma which has spread from the original site of growth to another anatomic site. "The recent success of CAR therapies suggests that with appropriate safety modifications, we can be cautiously optimistic regarding the potential development of a CSPG4-specific CAR therapy for the treatment of metastatic cancer." (PMID 25197555, 2014).
myeloid leukemia (1 paper, 2019). A clonal proliferation of myeloid cells and their precursors in the bone marrow, peripheral blood, and spleen. "Although CSPG4 presence has been confirmed in lymphoid and myeloid leukemias, CSPG4 seems to be primarily expressed in 11q23 rearranged MLL." (PMID 31779130, 2019).
nasopharyngeal carcinoma (1 paper, 2023). A carcinoma arising from the nasopharyngeal epithelium. "Similar results were also observed in the CSPG4.CAR-T cells killing assay using CSPG4+ nasopharyngeal cancer cell line CNE-2." (PMID 36882513, 2023).
nevus (1 paper, 2025). Nevus (or naevus, plural nevi or naevi, from nævus, Latin for "birthmark") is the medical term for sharply circumscribed[1] and chronic lesions of the skin or mucosa. "Nevus cells in melanocytic lesions exhibit a different differentiation stage or altered maturation compared with normal melanocytes of the skin and may harbor genetic changes that can result in altered CSPG4 expression, as observed with anti‐BRAF immunostaining." (PMID 40700516, 2025).
non-small cell lung carcinoma (1 paper, 2014). A group of at least three distinct histological types of lung cancer, including non-small cell squamous cell carcinoma, adenocarcinoma, and large cell carcinoma. "Each of the CSPG4 CAR transduced PBL cultures yielded IFN-γ effector cytokine release with considerably lower levels observed with the CSPG4-negative non-small cell lung cancer line H1299." (PMID 25197555, 2014).
oligoastrocytoma (1 paper, 2018). A WHO grade II tumor composed of a conspicuous mixture of two distinct neoplastic cell types morphologically resembling the tumor cells in oligodendroglioma and diffuse astrocytoma. "NG2/CSPG4, PDGFRα, Olig2, Sox10, and Nkx2.2 were preferentially found in human diffuse gliomas with oligodendroglioma or oligoastrocytoma morphology." (PMID 30213051, 2018).
Pancreatic Diseases (1 paper, 2014). "Apparently, any pancreatic disease is capable of altering CSPG4 production, whether remote or local, via intrinsic or extrinsic mechanisms." (PMID 24932730, 2014).
papillary thyroid carcinoma (1 paper, 2025). "Interestingly, we observed that the mRNA level of both TAs was higher in ATC patients as compared to follicular and papillary thyroid cancers, suggesting a potential association between increased B7-H3 and CSPG4 expression levels with a higher degree of tumor aggressiveness." (PMID 40847369, 2025).
periventricular leukomalacia (1 paper, 2025). Periventricular leukomalacia (PVL) is a brain injury disorder characterized by the death of the white matter of the brain due to softening of the brain tissue. "Bioinformatic analysis indicates that chondroitin sulfate proteoglycan 4 (CSPG4) is discovered as a CSF biomarker and positively correlated with the ventricular size and the rate of periventricular leukomalacia." (PMID 39686677, 2025).
Pleural effusion (1 paper, 2018). The presence of an excessive amount of fluid in the pleural cavity. "Previous studies using CSPG4-specific mAbs have shown that CSPG4 is expressed on nearly 73% of primary TNBC patient specimens, malignant cells in pleural effusions from patients with TNBC, human TNBC cells and CICs cultured in vitro, and TNBC xenograft tumors grown in immunodeficient mice." (PMID 29561763, 2018).
proteinopathies (1 paper, 2025). "Identification of CSPG4 through proximity labeling extends this concept to C9orf72-associated ALS/FTD, suggesting convergence of pathogenic mechanisms across multiple proteinopathies." (PMID 41394638, 2025).
rhabdomyosarcoma (1 paper, 2022). A rare aggressive malignant mesenchymal neoplasm arising from skeletal muscle. "Nevertheless, other proteoglycans are also involved in rhabdomyosarcoma, such as chondroitin sulfate proteoglycan 4 (CSPG4) and glypican-3 (GPC3)." (PMID 35128576, 2022).
thyroid tumor (1 paper, 2025). A benign or malignant neoplasm affecting the thyroid gland. "To confirm in vivo the antitumor activity of CSPG4 CAR T cells, we tested their ability to eradicate thyroid tumors in a xenograft murine model of ATC." (PMID 40847369, 2025).